MIR8073 (microRNA 8073)
Synonyms: hsa-mir-8073
Gene: MicroRNA gene on chromosome 13 (110,340,958 to 110,341,029, forward strand). Ensembl gene ENSG00000276765.
Homologues: Orthologues: chimpanzee MIR8073 (100% identical).
Diseases named in the same sentence as MIR8073 in open-access papers:
MIR8073 is named in the same sentence as 1 disease in open-access papers, as found by Europe PMC text mining. Sharing a sentence is not in itself a finding about the gene and the disease.
MIR8073 shares sentences with these, for which no sentence is quoted: Parkinson disease (1 paper).